ABL1 (ABL proto-oncogene 1, non-receptor tyrosine kinase)
Diseases named in the same sentence as ABL1 in open-access papers (continued):
Sharing a sentence is not in itself a finding about the gene and the disease.
tumor (continued). "We evaluated the expression levels of the following five genes associated with DNA damage, carcinogenesis, and/or chemoprevention mechanisms: the tumor suppressors ETV6 and PTEN, the cell death regulators BCL2 and BAX (anti- and proapoptotic, respectively), and the protooncogene ABL1." (PMID 30370304, 2018). "The NRP1 cytoplasmic domain has also been reported to interact with the non-receptor tyrosine kinase ABL1 in tumour cells." (PMID 26923176, 2016). "Xu and colleagues demonstrated that tumor irradiation of C57BL/6 mice implanted with syngeneic RM-1 prostate cancer cells led to an increase in CSF1 expression by the tumor cells, which was dependent on activation of ABL-1 tyrosine kinase." (PMID 24829747, 2013). "Interestingly, COSMIC fusion BCR::ABL1 was not tumor enriched in our analysis, likely due to paucity of the relevant tumors in TCGA." (PMID 37323575, 2023). "However, three SNPs found in genes such as ALK, KDR, and ABL1 in the HBL tumor in this study were not reported in UCSC, COSMIC, and ClinVar databases." (PMID 37273678, 2023). "Interestingly, and in sharp contrast to KMT2A-r models, BCL-2+BCR::ABL1 mutated samples did not respond to VEN application, with similar blast kinetics and tumor cell frequencies in controls and treated animals." (PMID 35778418, 2022). "In this study, FOXM1 may be phosphorylated by cytoplasmic ABL1 in response to stimuli and induces tumorigenesis, while FOXM1 phosphorylated in the nucleus contributed to cell proliferation, particularly in the cells with ABL1 overexpression and activation, especially in the tumor cells." (PMID 39060421, 2024). "While the degree of MLH1 protein reduction was roughly equivalent between pharmacological inhibition and siRNA knockdown of ABL1 in HEK293 cells, we cannot rule out the possibility that either c-Kit or PDGFR may influence MMR in specific tumor backgrounds where they are highly expressed or mutated." (PMID 36338985, 2022). "Here, we show that ABL1, a nonreceptor tyrosine kinase, contributes to the high expression of FOXM1 and FOXM1-dependent tumor development." (PMID 39060421, 2024). "All signaling pathway inhibitors have pronounced negative effects on the viability of both GBM tumor cell lines but U87MGvIII is significantly more sensitive to the inhibition of casein kinase than the wild-type whereas the wild-type is more sensitive to the inhibition of PLCG1, ABL1 and BCL2." (PMID 31386654, 2019).
hematologic malignancies (39 papers, 2012 to 2026). "ETV6::ABL1 gene fusion is a rare recurrent genomic rearrangement associated with hematologic malignancies, and frequently occurs with additional anomalies." (PMID 37895201, 2023). "ABL1 fusion protein have been often described as a cause of resistance to therapy, also related to the development of mutant clones in relapsed hematologic malignancies." (PMID 27821800, 2016). "Previous studies have shown that low levels of YAP1 can block ABL1-induced apoptosis in hematological malignancies, while the genetic inactivation of MST1 restores YAP1 levels and causes cell death, both in vitro and in vivo." (PMID 40573272, 2025). "Deletion of ABL1 was detected in a cohort of hematologic malignancies carrying AML1-ETO and NUP98 fusion proteins." (PMID 36959186, 2023). "Chromosomal translocations generate the aberrant fusion TKs, such as BCR-ABL1, Ets variant gene 6-ABL1 [TEL(ETV6)/ABL1], TEL(ETV6)/JAK2, and TEL-platelet-derived growth factor beta receptor [TEL(ETV6)/PDGFβR], which induce hematologic malignancies." (PMID 27233483, 2016). "TEL fusion proteins with other tyrosine kinases, such as ABL1, ABL2, JAK2, NTRK3, FFGR3, and PDGFRB, have also been associated with various hematologic malignancies, though direct comparisons between these fusion proteins in mouse models is not complete." (PMID 24116232, 2013). "ETV6::ABL1 rearranged neoplasms are rare hematological diseases." (PMID 38203288, 2023). "This is supported by the synergism between TKIs and chemotherapy, which have been proven to be successful in the treatment of other hematological malignancies, including B-cell acute lymphoid leukemia with BCR::ABL1 fusion." (PMID 39457651, 2024). "Multiple chromosomal rearrangements involving ETV6 (such as ETV6::RUNX1, ETV6::ABL1, ETV6::NTRK3, and ETV6::ACSL6) have been demonstrated to play a crucial role in the development of several hematologic diseases such as AML, as well as in their diagnosis and prognosis." (PMID 39723366, 2024).
infection (30 papers, 2009 to 2025). The state of being infected such as from the introduction of a foreign agent such as serum, vaccine, antigenic substance or organism. "To understand why ablating ABL1 impacted pathogenicity, we next examined infection-related development by Δabl1 mutant strains and found that the observed loss of rice infection was in major part due to impaired appressorium formation and function." (PMID 28072818, 2017). "To investigate this compensatory mechanism further, we generated a series of double mutants for lys-7 and the three candidate genes (abl-1, fat-5 and rga-6) identified by resistance analysis, and tested their susceptibility to infection with C. neoformans and S. Typhimurium." (PMID 21399680, 2011). "AnkA interacts with ABI1, and inhibition of ABL1 by siRNA knockdown or by imatinib impairs infection." (PMID 39354505, 2024). "Here, we used protocols to selectively quantify infection via virus-membrane and membrane-membrane fusion and found that the imatinib effect on these processes are both Abl1 and Abl2 refractory." (PMID 35388061, 2022). "qRT-PCR results showed an increased expression of GC genes abl1 and tff-2 in infection-IV in comparison to infection-I and -II, whereas the expression of gankyrin was significantly higher in infection-III and -IV than in infection-I and -II." (PMID 34585958, 2021). "Further, we determined an increased abl1 expression in all infection models in comparison to uninfected control after 24 hpi." (PMID 34585958, 2021). "Surprisingly, the expression of abl1 was downregulated in infection-III and -IV compared to infection-I and -II after 48 hpi." (PMID 34585958, 2021). "In particular, AnkA facilitates intracellular infection by activating the Abl-1 signaling pathway and by manipulating host cell processes in its interactions with the Anaplasma translocated substrate 1 (Ats-1) protein." (PMID 25487348, 2014). "A. phagocytophilum AnkA protein was found to translocate into host cells via the T4SS, where it localized to the cytosol and nucleus and was phosphorylated by Abl-1 to facilitate infection." (PMID 25166298, 2014). "Here, we discovered and characterized a negative-acting TOR regulator, encoded by ABL1, necessary for infection-related development of the rice pathogen Magnaporthe oryzae." (PMID 28072818, 2017). "Here, we provide functional evidence from the devastating rice blast fungus Magnaporthe oryzae that glucose can mediate TOR activity via the product of a novel carbon-responsive gene, ABL1, in order to tune cell cycle progression during infection-related development." (PMID 28072818, 2017). "To understand what role ABL1 might play in glucose signaling, fungal physiology and/ or host infection, we deleted the ABL1 gene from the M. oryzae genome." (PMID 28072818, 2017). "Further, in apparent contradiction, silencing of abl1 using siRNA has been reported to increase M. tuberculosis replication in macrophages suggesting that this family of kinases may play complicated roles during infection." (PMID 24586159, 2014). "We used the rescued strain rSczy3 to infect CEKs and performed qRT-PCR to evaluate the relative expression levels of CTSL, CTSB, Abl1, Abl2, IFITM3, ADAM17, TMPRSS2, NRP1, and CD74 at 12 and 24 h post-infection." (PMID 37376546, 2023). "Thus the enhanced survival of lys-7 and abl-1 knockout animals is due to an increased tolerance of S. Typhimurium within the gut, rather than resistance to infection or limitation of bacterial growth." (PMID 21399680, 2011). "Infection of both SARS-CoV-2 and a surrogate lenti-Spike were blocked by imatinib, a widely used inhibitor of the non-receptor Abl1 and Abl2 tyrosine kinases." (PMID 35388061, 2022).
neurodegenerative disease (29 papers, 2012 to 2025). A disorder of the central nervous system characterized by gradual and progressive loss of neural tissue and neurologic function. "Putative interaction between ERVK IN and ABL1 may have been important for ERVK integration into germline cells, and it may additionally play a role in ERVK expression, specifically in neurodegenerative disease displaying enhanced ABL1 activity." (PMID 34361946, 2021).
blood cancer (12 papers, 2012 to 2025). "CML is a blood cancer that is treated with Abl1 inhibitors, and is often seen as a model for targeted therapy and drug resistance." (PMID 39509464, 2024). "Further, it was demonstrated that PTPN11 is necessary for BCR::ABL1-induced hematologic neoplasms, as its deletion compromised induction of CML in mice." (PMID 37384296, 2023). "CML is a hematologic neoplasm sustained by the constitutive activation of the BCR::ABL1 fusion kinase that can successfully be targeted with TKIs, so that most CML patients nowadays obtain durable remissions." (PMID 35992847, 2022). "CML is a blood cancer that is treated with drugs called Abl1 inhibitors." (PMID 39509464, 2024). "For ABL1, the longest bar is ‘Haematopoietic & Lymphoid’, highlighting its impact in blood cancers." (PMID 27899578, 2017).
hematopoietic neoplasm (10 papers, 2011 to 2025). "In chronic myeloid leukemia (CML), the hematopoietic neoplasm is predominantly caused by the formation of the BCR::ABL1 kinase." (PMID 37384296, 2023). "In hematological tumors, it is known that DNA damage leads to the activation of a pro-apoptotic pathway through the nuclear relocation of ABL1 kinase." (PMID 40573272, 2025). "In hematological cancer, low YAP level prevents nuclear ABL1-induced apoptosis and rescued YAP expression triggers cell death." (PMID 35967587, 2022). "miRNA-203 is silenced in CML due to genetic and epigenetic (promoter CpG hypermethylation) mechanisms, where a correlation between hypermethylation and decrease expression of miRNA-203 in BCR-ABL1 positive CML cell lines but not in hematopoietic neoplasms without ABL1 alterations." (PMID 34830398, 2021).
neurological diseases (3 papers, 2012 to 2024). "Reportedly, ABL1 is involved in mitochondrial activity, ATP metabolism, protein translation and metabolism, and numerous neurological disorders." (PMID 38584839, 2024).
adenocarcinoma (2 papers, 2019 to 2025). A common cancer characterized by the presence of malignant glandular cells. "KRAS, ARID1A, ABL1, ATM, RET, and CDH1 mutations have been detected in the mesonephric adenocarcinomas containing sex cord-like pattern; among these genes, KRAS mutation was the most frequent." (PMID 31739799, 2019).
infectious disease (2 papers, 2025). A disorder directly resulting from the presence and activity of a microbial, viral, or parasitic agent in humans. "In the MULTI group, we identified activation of CRH-related infectious disease response pathways, marked by ABL1 phosphorylation at S183." (PMID 40842862, 2025).
immune disorders (1 paper, 2021). "Kinase signal transduction inhibitors, such as trametinib and imatinib, block the ABL1, ERK–MAPK and PI3K–AKT–mTOR pathways, potentially preventing early virus invasion and resulting immune disorders." (PMID 33726861, 2021).
ABL1 also shares sentences with these, for which no sentence is quoted: Alzheimer disease (16 papers); myelodysplastic syndrome (14); B-cell acute lymphoblastic leukaemia (9); diabetes (8); neuroblastoma (7); atherosclerosis (6); Ewing sarcoma (6); thrombosis (6); α-synucleinopathies (6); breast tumors (5); cognitive decline (5); Cognitive impairment (5); hypereosinophilic syndrome (5); Parkinson's (5); anemia (4); chronic myelomonocytic leukemia (4); endothelial dysfunction (4); Huntington disease (4); osteoporosis (4); pancreatic cancer (4); pulmonary fibrosis (4); pulmonary hypertension (4); asthma (3); B cell lymphoma (3); Burkitt lymphoma (3); dementia (3); Down syndrome (3); head and neck cancer (3); heart failure (3); Hyperglycemia (3).
A further 203 diseases each share a sentence with ABL1 in 3 papers or fewer.